PRL (prolactin)
Diseases named in the same sentence as PRL in open-access papers (continued):
Sharing a sentence is not in itself a finding about the gene and the disease.
cancer (continued). "Consequently, our results demonstrate a novel role of prolactin in the regulation of iron transport and provide first-hand evidence for the direct transfer of iron from macrophages to cancer cells." (PMID 39201626, 2024). "The concept of the locally produced PRL at sites of tissue pathosis via activating its receptor on target cells has emerged as a new mechanism in various pathologic contexts, including inflammation and cancer." (PMID 36717425, 2023). "Leptin, ferritin, FGF2, and prolactin may potentiate cancer stem cell formation; ferritin also impacts pathways leading to the EMT transition." (PMID 37857666, 2023). "When downstream KEGG analysis was performed, the pathways for the upregulated miRNAs found in the semen samples included, amongst others, the prolactin signaling pathway (for hsa-miR-1181), miRNAs in cancer (for hsa-miR-202-3p), and thyroid hormone signaling pathway (for hsa-miR-935)." (PMID 36983773, 2023). "This TNBC subset was found to be more differentiated, supporting the hypothesis that PRL drives a pro-differentiation program in these cancers." (PMID 35784527, 2022). "Interestingly, LAT1/SLC7A5, a transporter for branched chain amino acids which is regulated by PRL during lactation, is highly expressed by tamoxifen resistant cancers." (PMID 35784527, 2022). "Independently from ovarian steroids, PRL can modulate the epithelial hierarchy and increase progenitor populations, drive development of ductal and alveolar abnormalities, and with time, promote aggressive metastatic ER+ carcinomas." (PMID 35784527, 2022). "This evidence highlights the important role that PRL has in cancer processes." (PMID 34745013, 2021). "An emerging role of prolactin (PRL) has been proposed in several different cancers including OC." (PMID 34358244, 2021). "Increased PRLR levels in tumors may therefore be a sign of increased PRL stimulated cancer cell growth." (PMID 34358244, 2021). "Recent findings demonstrate that PRL production is not only restricted to the pituitary gland, and extra-pituitary PRL production may be of relevance in cancer." (PMID 34358244, 2021). "PRL extract shows potent anticancer activity against cancer cell lines." (PMID 34070179, 2021). "The role of PRL in apoptosis inhibition in cells of the immune system such as thymocytes and T cells, and during B cell maturation in the BM, as well as in breast and ovarian cancer cells has been previously documented." (PMID 33557010, 2021). "Additionally, multiple known endocrine hormones, such as insulin, prostaglandins, glucocorticoids, prolactin, and progesterone, have been observed to play a role in cancers by modulating malignant phenotypes or anti-tumor immune responses." (PMID 33117814, 2020). "Cluster 1 was related to endocrine resistance, prolactin signaling pathway, and pathways in cancer." (PMID 32210799, 2020). "Many studies have suggested a role for PRL in different forms of cancers." (PMID 32121009, 2020). "In addition to intra-cranial, the metastasis of ACTH-secreting carcinomas has a predilection for the liver and spinal, and the metastasis of PRL-secreting carcinomas exhibits preferences for lymph nodes and bones." (PMID 33643220, 2020). "Interestingly, prolactin signaling has also been shown to promote metastasis by inducing cell motility and also confers resistance to cancer cells to chemotherapeutic agents." (PMID 31795960, 2019). "The analysis of the predicted targets and pathways revealed that in SCLE, miR-21 was linked with Hippo signaling, bacterial invasion of epithelial cells, transcriptional regulation of cancer, prolactin signaling, FoxO signaling, and biosynthesis and degradation of fatty acids." (PMID 32082077, 2019). "Moreover, the prolactin-signaling pathway was also identified as another overlooked aspect of cancer initiation, which was highly enriched in our CIGs (adjusted P-value = 2.07E-20)." (PMID 30045691, 2018).
cancer (continued). "However, activation of the canonical mediator of prolactin, STAT5, is associated with more differentiated cancers and better prognoses." (PMID 28103936, 2017). "Prolactin promotes a variety of cancers by an array of different mechanisms." (PMID 28422740, 2017). "In addition, more and more evidence has accumulated indicating that prolactin promotes tumorigenesis in various types of cancers, including breast, prostate, ovary, liver, and brain, as well as stimulating the growth of pituitary tumors." (PMID 28422740, 2017). "PRL and mammographic density are epidemiologically linked and PRL enhances the expression of mammary ECM components such as Col1a1, and Tnc, which promotes cancer cell invasion." (PMID 28103936, 2017). "Indeed, escalated plasma prolactin levels are often found in patients with developed and late-stage cancers." (PMID 27184120, 2016). "These by maximizing the actions of endogenous prolactin could have a role in cancer progression and resistance to endocrine therapy." (PMID 27564112, 2016). "Similarly, high PRL concentrations in serum and tissue homogenates were previously shown in dogs suffering from malignant tumors." (PMID 26370564, 2015). "This approach may include possible effects of a malignant neoplasm on the remaining mammary gland, i.e., altering its gene expression levels or influencing sex steroid and PRL serum levels." (PMID 26370564, 2015). "Only PRLR in malignant tumors seems to be influenced by circulating PRL levels." (PMID 26370564, 2015). "This controversial view of PRL in human cancer has been considerably modified in the past 10 years." (PMID 24148306, 2013). "Since epidemiologic studies closely link prolactin and the development of ERα+ tumors in women, we examined characteristics of the aggressive ERα+ and ERα- carcinomas which develop in response to mammary prolactin in a murine transgenic model (neu-related lipocalin- prolactin (NRL-PRL))." (PMID 21276249, 2011). "Additionally, PRL may regulate the actin cytoskeleton via the Src pathway, thereby promoting cancer cell proliferation, a significant factor in the development of cancer." (PMID 40303287, 2025). "Furthermore, the aim of this study was to assess the effect of HPL on cancer risk, irrespective of the etiology of the elevated PRL levels." (PMID 40478803, 2025). "Thus, studies have been conducted to further explore whether the autocrine PRL expressed by cancer cells could contribute to cancer progression." (PMID 38898487, 2024). "It was preliminarily predicted that NR could regulate the targets of CASP3, AKT1,ESR1,ACTB,MAPK3 and may modulate various pathways like estrogen signaling, thyroid hormone signaling pathway, prolactin signaling pathway, proteoglycan in cancer pathway, endocrine resistance pathway." (PMID 36401485, 2022). "Many of the remaining 20% of experimental PRL-induced cancers exhibited elevated pAKT, but not pERK1/2, consistent with driver mutations in the phosphatidylinositol-3-kinase pathway, common in many clinical ER+ cancers." (PMID 35784527, 2022). "Due to the chances of infertility and developing cancer, blood prolactin levels could be monitored." (PMID 36619589, 2022). "Increased PRLR levels in tumors may therefore stimulate cancer cell growth via PRL." (PMID 32121009, 2020). "In addition to the endocrine (circulating) concentrations, locally produced prolactin may promote cancer development via autocrine and paracrine effects." (PMID 25887963, 2015). "Therefore as previously proposed in cancer cells, ligand-induced complex imported to the nuclei might mediate some genetic effects of PRL in activated monocytes." (PMID 23731754, 2013).
cancer (continued). "Although it has been extensively described that ev21 causes the negative side effects of the K allele, the findings of this study might also indicate involvement of PRLR. prolactin and its receptor are involved in the growth of different forms of cancer, egg production, and in the immune system." (PMID 18713476, 2008). "In this study, the link between increased levels of PRL observed during pregnancy, overactivation of the PRL/STAT3/JAG1 pathway in CRC, and increased EMT and cancer cell stemness was established by in vitro and in silico experimentation." (PMID 41501898, 2026). "KEGG pathway analysis indicated that Duhuo is involved in multiple signaling pathways, including those related to cancer, MAPK, PI3K-Akt, and prolactin." (PMID 41496007, 2026). "For the first time, we demonstrate that pregnancy-level PRL directly enhances JAK2/STAT3 and JAG1/NOTCH1 signaling in CRC cells, promoting epithelial-mesenchymal transition (EMT) and cancer stem-like protein expression." (PMID 41501898, 2026). "In vitro data was then used to link pregnancy levels of PRL to increased JAK2/STAT3 and JAG1/NOTCH1 signaling resulting in increased epithelial-to-mesenchymal transition (EMT) and cancer cell stem-like protein expression." (PMID 41501898, 2026). "Enrichment results indicated involvement in cancer signaling, the MAPK pathway, PI3K-Akt signaling, and the prolactin signaling pathway." (PMID 41496007, 2026). "This allows us to further investigate the link at a cellular level between the increased cancer aggressiveness observed in pregnant CRC patients and the activation of EMT and stemness pathways due to high PRL levels in the third trimester." (PMID 41501898, 2026). "Consequently, we were not able to determine whether cancer risk differs between patients with persistently elevated PRL levels and those with normalized levels, or if there is a correlation between the degree of PRL elevation and cancer risk." (PMID 40478803, 2025). "The PRL/ARL/CNNM/TRPM complex, recently named the PACT complex, has been well described in heterologous overexpression systems and only few studies demonstrated the involvement of PRL and CNNM in cancer." (PMID 41395111, 2025). "The varying expressions of these molecules in response to stimuli, such as PRL and DOX, underscore their importance in cancer progression and treatment response." (PMID 40003884, 2025). "In EOC, PRL-JAK-STAT pathway signalling can lead to phosphorylation of STAT3 and STAT5, connecting PRL signalling to EMT, EOC cancer stemness and resistance to therapy." (PMID 39285292, 2024). "Regarding HRAS mutant cancer cells, the downregulated pathways included Wnt signaling, HIF-1 signaling, glucagon signaling, Prolactin signaling, and Hippo signaling." (PMID 38982514, 2024). "KEGG pathway analysis identified 124 pathways, with notable enrichments observed in the MAPK signaling pathway, pathways in cancer, the AGE-RAGE signaling pathway in diabetic complications, and the prolactin signaling pathway." (PMID 39125368, 2024). "Pathway analysis of target genes using KEGG 2021 HUMAN and DisGeNET revealed top pathways including cancer and EOC-related regulation, as well as prolactin signalling pathways." (PMID 39285292, 2024). "Furthermore, the response seen with tamoxifen monotherapy in a patient with prolactin-secreting cancer suggests that tamoxifen might have a direct effect on prolactin secretion that is independent of DA action, yet the magnitude of this effect remains to be elucidated." (PMID 36950000, 2023). "Due to the strong evidence supporting the critical role of PRL and PRLR in human cancers, various approaches have attempted to modulate activity both by suppressing downstream signaling as well as by developing PRLR antagonists." (PMID 36714582, 2022).
cancer (continued). "For the purpose of meta-analysis, proteomic markers were classed as cancer antigens (CA-15.3, CA-19.9, CA-72.4, CEA), hormones (leptin, visfatin, prolactin) and other proteomic markers (G-CSF, YKL-40 and DJ-1)." (PMID 36230588, 2022). "Functional analysis by the PANTHER pipeline on cancer-related MXE showed additional functional enrichments, in signalling process (e.g. oxytocin, adipocytokine and prolactin) and regulatory pathway (e.g. insulin secretion, transcription) (FDR level <0.01)." (PMID 33651795, 2021). "The most significantly enriched pathways were the TNF signalling pathway, prolactin signalling pathway, NF-κB signalling pathway, HTLV-1 infection, pathways in cancer, etc." (PMID 34259096, 2021). "Furthermore, H53 could inhibit PRL/GH-driven cancer cell proliferation in vivo and in vitro." (PMID 33362552, 2020). "The top pathways (count number ≥ 15) included cancer, PI3K-AKT, MAPK, TNF, focal adhesion, prolactin, HIF-1, thyroid hormone, FoxO, Rap1 and Ras signaling pathways." (PMID 32450873, 2020). "In one series, PRL-secreting PCs spread systemically more often (71%) than ACTH-secreting PCs (57%); in contrast, growth hormone (GH)-secreting carcinomas present more commonly with cerebrospinal metastasis." (PMID 33643220, 2020). "Prolactin secreting carcinomas express transcription factors Pit-1 and ER while ACTH-secreting carcinomas express T-PIT." (PMID 32622369, 2020). "The ROC analysis comparing patients with ICC to Ctrl HPV− revealed that five tested cancer biomarkers: TNFα, CYFRA 21-1, macrophage migration inhibitory factor (MIF), prolactin and SCF had AUC greater than 0.8." (PMID 31089160, 2019). "We identified important cancer related pathways, pancreas specific pathways, AGE-RAGE signaling, prolactin signaling and insulin resistance signaling pathways among the most affected ones." (PMID 31795960, 2019). "With the stability and accuracy, we can find Her-ELISA, PDGF-AA, Prolactin and TTR is the best biomarkers for classifying cancer samples from healthy to cancer data." (PMID 30396341, 2018). "This remodeling of the surrounding ECM in conjunction with the ability of PRL to increase the expression of mammary ECM components, suggests a feedforward loop by which PRL can drive the metastasis of ERα + cancers." (PMID 28103936, 2017). "Increased expression of miR-106b replicated, and anti-miR-106b counteracted, the effects of prolactin on degradation of the 3′UTR construct, p21 mRNA levels, and cell proliferation in breast (T47D) and prostate (PC3) cancer cells." (PMID 28422740, 2017). "We trust that, by inhibiting the formation of PRL-CNNM complexes, we are opening new avenues in cancer therapy suitable to a large array of human cancer types where PRLs are overexpressed." (PMID 26969161, 2016). "Specifically, we examined the expression of Akt1m in primary cancers from BRCA1 conditional knockout mice (Brca1-/-), PtenG129E mutant females as well as transgenic mice that overexpress ERBB2 (MMTV-neu) and prolactin (NRL-PRL)." (PMID 24628780, 2014). "However, although shown to be potentially useful as a member of multi-marker diagnostic panels, none of these studies could establish prolactin as an independent cancer marker." (PMID 23874805, 2013). "Outside of the pituitary, a small amount of prolactin can be produced by non-lactotrophs, including mammary epithelia and a variety of cancer cells as an autocrine survival factor." (PMID 39201626, 2024). "These genes exhibit extensive interactions with others in potential pathways such as the MAPK signaling pathway, pathways in cancer, the AGE-RAGE signaling pathway in diabetic complications, the prolactin signaling pathway, and growth hormone synthesis, secretion, and action." (PMID 39125368, 2024).
cancer (continued). "Regarding HRAS mutant cancer cells, the downregulated pathways via Kegg enrichment analysis included Wnt signaling, hypoxia-inducible factor 1 (HIF-1) signaling, glucagon signaling, Prolactin signaling, and Hippo signaling, among others." (PMID 38982514, 2024). "In fact, an animal model of PRL-induced breast carcinogenesis demonstrated that JAK2 is needed for cancer initiation but not for maintenance of tumors." (PMID 37834225, 2023). "Prolactin (PRL)-dependent signaling occurs as the result of ligand-induced dimerization of the prolactin receptor, their interaction can modulate the endocrine and autocrine effects of prolactin in normal tissue and cancer." (PMID 37490712, 2023). "Enrichment pathways analysis with target genes of top 10 bEV miRNAs demonstrated that cancer, epidermal growth factor receptor (EGFR), prolactin signaling pathway, erythroblastic leukemia viral oncogene homologue (ErbB), and forkhead box, class O (FoxO) signaling pathways are enriched." (PMID 36313069, 2022). "Due to the extensive expression of PRL and PRLR in various tissues, and the efficacy of preclinical inhibitory strategies, it is clear that the PRL : PRLR signaling axis is a critical pathway in human biology and cancers." (PMID 36714582, 2022). "The observed negative moderate correlation between TC or HDL and prolactin was much more significant in cancer cases (rho = −0.56 and −0.41 in the positive cohort, against rho = −0.22 and −0.18 in the control group)." (PMID 35323711, 2022). "In conclusion, PCBs can interfere with thyroid hormone dysfunction by regulating MAPK3, MAPK1, RXRA, PIK3R1, and other potential targets, as well as the cancer pathway, PI3K-Akt signaling pathway, thyroid hormone signaling pathway, prolactin signaling pathway, and FoxO signaling pathway." (PMID 36203481, 2022). "After adjustment of the p-value, the top 15 pathways encompassed proteoglycans in cancer, PI3K-Akt signaling pathway, ErbB signaling pathway, Pathways in cancer, Estrogen signaling pathway, Focal adhesion, Ras signaling pathway, and Prolactin signaling pathway." (PMID 36313358, 2022). "As presented here, the roles for the serine residues of STAT5a are nonredundant, exhibiting different effects on cancer characteristics, and different regulatory roles on the canonical pathway of PRL/STAT5a signaling." (PMID 34188118, 2021). "Besides, it has been observed that some infections can regulate the PRL/PRLR axis, thus favoring cancer progression." (PMID 34745013, 2021). "The initial step in PRL action is the binding to a specific membrane receptor, the PRLR, which belongs to the class 1 cytokine receptor superfamily and has been a therapeutic target in treating cancer." (PMID 34158080, 2021). "PRL and its receptor (PRLR) activate a series of effects such as survival, cellular proliferation, migration, invasion, metastasis, and resistance to treatment, being highly relevant in developing certain types of cancer." (PMID 34745013, 2021). "The secretion of prolactin remarkably increases during pregnancy and lactation 46, implying that PRL/PRLR might contribute to the correlation between cancer development and pregnancy/lactation." (PMID 33664869, 2021). "Peptide receptor radionuclide therapy (PRRT) is another challenging therapy for non-medical management of PRL-producing carcinomas." (PMID 32760348, 2020). "Further investigation showed that it could efficiently prevent prolactin mediated phosphorylation of STAT5 at 100 nM concentration and above, similar to the PrlRA itself, suggesting a potential as drug for cancer therapy in the future." (PMID 31063493, 2019).